MSLNL (mesothelin like)
Description:
May play a role in cellular adhesion.
Synonyms: C16orf37; MPFL
Gene: Protein-coding gene on chromosome 16 (769,428 to 782,054, reverse strand). Ensembl gene ENSG00000162006.
Subcellular location: Membrane
Homologues: Orthologues: pig MSLNL (57% identical), guinea pig MSLNL (53% identical), rat Mslnl (52% identical), mouse Mslnl (51% identical), dog MSLNL (51% identical), zebrafish mslna (22% identical), zebrafish si:ch211-188p14.4 (17% identical), zebrafish si:ch211-188p14.5 (9% identical). Paralogues in human: MSLN (19% identical), OTOA (13% identical), STRC (12% identical).
Diseases named in the same sentence as MSLNL in open-access papers:
MSLNL is named in the same sentence as 3 diseases in open-access papers, as found by Europe PMC text mining. Sharing a sentence is not in itself a finding about the gene and the disease. The quoted sentences say what the papers report.
pan (1 paper, 2023). "In pan cancer, NXF2B, MSLNL, PCGF1, INO80B-WBP1, LBX2-AS1, MRPL53, LBX2, TTC31, WDR54 and WBP1 were co-altered in the TLX2-altered group." (PMID 37758722, 2023).
MSLNL also shares sentences with these, for which no sentence is quoted: cancer (1 paper); tumor (1).